BDNF (brain derived neurotrophic factor)
Diseases named in the same sentence as BDNF in open-access papers (continued):
Sharing a sentence is not in itself a finding about the gene and the disease.
neurological disorders (continued). "Alterations of BDNF level have been implicated in a large range of neurological disorders." (PMID 33333158, 2021). "Brain-derived neurotrophic factor (BDNF) is another growth factor which plays a central role in the survival and differentiation of neurons, but apart from nervous system disorders, several reports documented an association between plasma BDNF and systemic or peripheral inflammatory conditions." (PMID 32280719, 2020). "In conclusion, we proved the neurogenic potential of several hb-HDACis, alongside their ability to enhance BDNF expression, which by modulating the neurogenesis and/or compensating for neuronal loss, could be propitious for treatment of neurological disorders." (PMID 30841499, 2019). "BDNF was implicated an important role in the pathogenesis of neurological disorders." (PMID 32038255, 2019). "Thus, many neurological disorders have been associated with BDNF, with abnormalities occurring anywhere from the transcription of the BDNF gene to the receptor-mediated signaling cascades." (PMID 22720171, 2012). "Therefore, establishing the causative role of BDNF in neurological disorders is crucial." (PMID 38707431, 2024). "Moreover, the single nucleotide polymorphism Val66Met of the BDNF gene may highlight the susceptibility to develop certain neurological disorders." (PMID 38268968, 2023). "Indeed, changes in blood BDNF levels have been associated with a number of neurological diseases including AD, and they have also been more frequently reported days or weeks after stimulation following tDCS in different clinical conditions or experimental models." (PMID 32719795, 2020). "Second, a previous study also found the activation of intracellular signaling pathways, especially brain-derived neurotrophic factor (BDNF)—tyrosine receptor kinase B (TrkB), may account for the positive link between RS utilization and lower risk of neurological disorders." (PMID 32923448, 2020). "Thus, alterations in BDNF levels and signaling have been implicated in many neurological diseases." (PMID 30730976, 2019). "Understanding the critical role of BDNF in the pathology of neurological diseases lays the groundwork for creating novel therapeutic techniques." (PMID 40149774, 2025). "Understanding the molecular mechanisms behind the reciprocal control of apoptosis by BDNF and its precursor, proBDNF, is essential for developing treatment for neurological diseases defined by excessive death." (PMID 40430064, 2025). "Brain-derived neurotrophic factor (BDNF) plays a critical role in protection against neurological diseases." (PMID 41488245, 2025). "Advanced tools such as single-cell RNA sequencing, spatial transcriptomics, and proteomics should be utilized to identify cell-type-specific roles of the BDNF/TrkB system across diverse neurological diseases." (PMID 40005159, 2025). "While BDNF presents a potential for therapeutic benefits for a variety of neurological disorders, clinical application of BDNF remains limited due to delivery difficulties, patient-to-patient variability, and complicated measurement." (PMID 40362507, 2025). "BDNF seems to play a relevant role in neurological diseases, especially in the context of acute inflammatory disease activity (i.e., acute relapse)." (PMID 39812717, 2025). "Due to its critical and very pleiotropic activity, reduction of BDNF levels and alterations in the BDNF/TrkB signaling are connected with a broad spectrum of neurological diseases." (PMID 40380033, 2025). "BDNF belongs to the category of neurotrophic factor, which has a wide range of roles in the central nervous system and affects the development of many neurological diseases." (PMID 38706359, 2025). "Studies have shown that surgery-induced neurological disorders can be ameliorated by restoring BDNF expression in vivo, so changes in BDNF levels in vivo can also respond to nervous system excitability to some extent." (PMID 40573191, 2025).
neurological disorders (continued). "So far, studies assessing the role of BDNF in pwMS as well as other neurological diseases were inconclusive." (PMID 39812717, 2025). "Studies have shown that BDNF is essential in neural development, memory formation, learning, and neurological diseases." (PMID 39839860, 2024). "This important role of BDNF in the striatum raises the question about its role in several neurological diseases involving the basal ganglia and what molecular and cellular mechanisms contribute to motor dysfunction." (PMID 39200225, 2024). "Although our study shows a significant correlation between serum BDNF levels and neurological disorders, it should be emphasized that direct mechanistic evidence of the relationship between the two has yet to be established." (PMID 39568824, 2024). "This study introduced a novel two-sample MR method for evaluating the bidirectional relationship between genetically predicted plasma BDNF levels and various neurological disorders, marking the first instance of such an approach." (PMID 38707431, 2024). "Informed consent was not required for this study because the large-scale GWAS summary statistics of plasma BDNF levels and various neurological disorders used were collected from previous studies." (PMID 38707431, 2024). "In this review, we have discussed the link between BDNF and platelets and their role in neurological disorders." (PMID 39568824, 2024). "The aim of this study is to analyze the complex relationship between BDNF and platelets, and their implications in neurological disorders." (PMID 39568824, 2024). "This article focuses on summarizing and analyzing the effects of BDNF on neurological diseases, cancer, and cardiovascular diseases to clarify its effects on these diseases and provide new ideas and methods for the treatment of these diseases." (PMID 39648800, 2024). "The following table provides an overview of the interplay between BDNF and platelets in neurological disorders, facilitating further exploration and understanding." (PMID 39568824, 2024). "By focusing on the role of platelets as reservoirs of BDNF, we aim to highlight possible therapeutic strategies for different neurological disorders where BDNF dysregulation is evident." (PMID 39568824, 2024). "Within the Mendelian randomisation framework, we used summary-level statistics for exposure (plasma BDNF levels) and outcomes (neurological disorders)." (PMID 38707431, 2024). "A case–control study included patients with different neurological disorders such as AD, Lewy body dementia, vascular dementia and frontotemporal dementia showed that BDNF serum levels were deregulated in those patients compared to healthy controls." (PMID 38752280, 2024). "This review highlights the diverse role of platelets in neurological disorders, focusing on their role as a storehouse of BDNF and other neurotrophic factors." (PMID 39568824, 2024). "The dysregulation of this interplay, such as an imbalance between proBDNF and mature BDNF or alterations in KCC2 expression or function, has been implicated in various neurological disorders and conditions." (PMID 38892438, 2024). "Despite uncertainties about how cleaved FNDC5 activates BDNF, these findings highlight a critical mechanism by which exercise benefits the central nervous system, offering potential therapeutic strategies for neurological disorders." (PMID 39935805, 2024). "As a result, we want to concentrate on BDNF in this article and outline its protective role against neurological disorders." (PMID 37287291, 2024). "In this review, we discuss the mechanisms through which BDNF functions in neurological diseases, cancer, and cardiovascular diseases." (PMID 39648800, 2024). "Its function is seldom investigated in neurological diseases; one recent report suggests that it is a key mediator of endocytic pathways in BDNF release." (PMID 39456006, 2024). "The effects of acupuncture on BDNF in various neurological diseases will be discussed separately below." (PMID 37780709, 2023).
neurological disorders (continued). "MSCs have recently been used as a platform of BDNF transportation for treating neurological disorders, including Huntington’s disease and ischemic stroke." (PMID 36986535, 2023). "Acupuncture demonstrates positive therapeutic effects on numerous neurological disorders by activating BDNF and its downstream signaling pathways." (PMID 37780709, 2023). "In our study in chronic HIV infection, we identified a strong association between plasma levels of SIRT2 with other prominent biomarkers of neurological disorders, such as BDNF, MAPT, and SNCA (32, –, 34)." (PMID 36719240, 2023). "Although studies generally suggest increasing BDNF levels and signaling would be beneficial for multiple neurological disorders, conflicting trends in BDNF levels have been reported in AD." (PMID 37508471, 2023). "Due to the numerous effects of BDNF on nervous system disorders, attention is being drawn to the potential of its therapeutic use." (PMID 36831706, 2023). "BDNF/TrkB signaling cascades in brain function regulation contribute to the therapeutic potential of BDNF/TrkB with respect to several neurological diseases, including TBI." (PMID 36986535, 2023). "Transcriptional regulation of the BDNF gene has important implications for the pathogenesis of many neurological disorders." (PMID 36582820, 2023). "This review focuses on recent research advances on the effect of acupuncture on BDNF and downstream signaling pathways in several neurological disorders." (PMID 37780709, 2023). "Under pathological conditions, the activation of BDNF signaling, potentiated by apigenin, is expected to relieve the patients from neurological diseases and emotional disorders." (PMID 37101380, 2023). "What do our findings mean for BDNF as a treatment for injuries or neurological disorders that are characterized by glutamate-induced excitotoxicity?" (PMID 38110605, 2023). "The role of BDNF in the aetiology of mental and neurological diseases is also reported as significant." (PMID 37108259, 2023). "For this reason, impairments of BDNF expression, signal transduction, transport, and metabolism remain fertile targets for investigation within progressive neurological disorders." (PMID 37626771, 2023). "In this review, BDNF expression is reduced in other neurological disorders, but acupuncture promotes neurological recovery by upregulating BDNF levels." (PMID 37780709, 2023). "Clinical trials have shown a decreased serum BDNF in neurological disorders, signifying BDNF as a potential biomarker." (PMID 39081970, 2023). "BDNF, as one of the most important neurotrophic factors in brain, is closely related to the pathophysiological process of many neurological diseases." (PMID 37545321, 2023). "Future in-depth studies on BDNF will be of great significance for determining the diagnosis and treatment of the neurological diseases mentioned in this article." (PMID 35814950, 2022). "Although, treatment with recombinant BDNF is beneficial in animal models of different neurological diseases, clinical trials with BDNF have generally been disappointing." (PMID 35845610, 2022). "Despite this evidence, BDNF serum levels are differently modulated by rTMS protocol in healthy individuals and different neurological disorders." (PMID 34410614, 2022). "Many other growth factors like brain derived neurotrophic factor (BDNF), protein kinase C, and interleukin 1 also interact with cannabinoid receptors and can be targeted as a therapeutic approach in the management of neurological diseases." (PMID 35628545, 2022). "A meta-analysis also showed that aerobic exercise increased BDNF levels in people with neurological disorders compared to the usual care or placebo group." (PMID 36316416, 2022). "In summary, BDNF has a significant role in the pathology of many neurological diseases, with inflammation of neurons serving as a primary trigger for the development of brain pathologies." (PMID 35625880, 2022).
neurological disorders (continued). "The neurotrophic role of mesencephalic astrocyte derived neurotrophic factor (MANF) and cerebral dopamine neurotrophic factor (CDNF) has been demonstrated in several models of neurological diseases and crosstalk with BDNF and GDNF." (PMID 36338029, 2022). "Especially, many plant-derived polyphenols with strong antioxidant and anti-inflammatory abilities, including quercetin, resveratrol, apigenin, and naringenin, can increase BDNF levels in several animal models of neurological disorders." (PMID 35651724, 2022). "It would be invigorating to look at how people with a reduced baseline BDNF level (as a result of psychiatric or neurological disorders) react to training with the inclusion of a vibrating platform." (PMID 36498182, 2022). "The main challenge in the use of BDNF as a therapeutic intervention in neurological disorders is its ability to reach the CNS in the desired concentration to elicit a therapeutic response." (PMID 35625880, 2022). "The promising actin-trophic activity of BDNF encouraged us to conduct other several studies, where this potential was exploited as a treatment in several neurological diseases." (PMID 36293164, 2022). "In the current study, we focused on two factors (hypoxia and inflammation), which are major players in the pathogenesis of neurological disorders, and two cell types (hippocampal neurons and astrocytes), which are major sources of BDNF in CNS." (PMID 35112804, 2022). "Taken together, these findings indicate that BDNF and its downstream signaling play a key role under normal conditions, as well as in the pathological states of many neurological diseases." (PMID 35814950, 2022). "It was notable that the ELISA assays used in previous reports of altered CSF BDNF in neurological disease appear insufficiently sensitive for the purpose." (PMID 33568689, 2021). "As a mimetic of BDNF, DHF has been gained a lot of attention as a therapeutic target in various BDNF-implicated human diseases, especially in neurological disorders." (PMID 34545064, 2021). "PGC‐1α/FNDC5/BDNF pathway is one of them whose importance in neuroprotection as an effective target in neurological diseases and ageing has been highlighted." (PMID 34018309, 2021). "In fact, early studies mainly focused on the role of BDNF in neurological diseases and found that BDNF had protective effects on cerebral ischemic injury." (PMID 33477900, 2021). "Ameliorating reduced brain-derived neurotrophic factor (BDNF) expression or maintaining high BDNF levels in the brain has been suggested to improve brain function in neurological diseases and prevent aging-related brain dysfunction." (PMID 34977362, 2021). "Previous studies mainly focused on its role in neurological diseases and found that BDNF had protective effects against cerebral ischemic injury." (PMID 33477900, 2021). "BDNF is the most abundant neurotrophin in brain tissue, and the serum level of BDNF has been suggested to function as a biomarker in some psychiatric and neurological diseases." (PMID 33628340, 2021). "Although many psychiatric and neurological disorders are associated with an increase in Glx/NAA, Met carriers of the BDNF SNP showed a decrease in this ratio." (PMID 33762638, 2021). "Use of DHF as a BDNF mimic has successfully provided neuroprotective effects in some relevant neurological diseases." (PMID 34855884, 2021). "The BDNF gene has been found to influence synaptic plasticity, and it has been indicated to play a role in a wide range of neurological diseases and injuries." (PMID 35273550, 2021). "Since BDNF plays a key role in the development and maturation of neurons, it has become the main therapeutic drug target for many neurological diseases." (PMID 35194435, 2021). "Improving BDNF expression and/or signaling has received a significant amount of attention regarding the treatment of a variety of neurological disorders, and a great deal of progress has been achieved by the RTT research community." (PMID 34281226, 2021).
neurological disorders (continued). "The combination of stem cells and BDNF-releasing nanomaterials holds great promise in regenerative medicine, especially in the treatment of neurological diseases." (PMID 35194435, 2021). "Alternatively, the administration of BDNF-inducing drugs has been shown to rescue different neurological diseases characterized by BDNF dysregulation." (PMID 32349283, 2020). "By uncovering the detailed mechanisms underlying how BDNF/TrkB couples with the eCB signaling pathway to modulate synaptic transmission, our study may provide a comprehensive understanding of how BDNF and eCBs associate in an overlapping set of neurologic diseases." (PMID 32948677, 2020). "This will enable better understanding of the involvement of BDNF expression in the pathogenesis and pathophysiology of neurological diseases." (PMID 32894176, 2020). "A recent study showed that serum brain-derived neurotrophic factor (BDNF) level is a useful biomarker not only to diagnose NPSLE from other neurological diseases like MS, but also to monitor the prognosis and response to treatment." (PMID 32825639, 2020). "Together, these studies made great strides toward BDNF-based therapeutics for neurological diseases." (PMID 32399020, 2020). "(B) Top 10 significantly enriched neurological diseases in the WP/RX2 vs. BDNF set of differentially expressed genes listed with their p-value from IPA." (PMID 31455240, 2019). "BDNF and NT-3 have previously undergone clinical evaluation as treatments for neurological disorders." (PMID 31671109, 2019). "BDNF is a neurotrophic factor that plays an important role in endogenous neurogenesis in physiological conditions and in the presence of neurological diseases." (PMID 30920178, 2019). "With regards to markers of BDNF gene activity, analyses have focused on DNA methylation of the BDNF promoter in various neurological disorders." (PMID 32038165, 2019). "(A) Top 10 significantly enriched neurological diseases in the BDNF transcriptome with their p-value (IPA)." (PMID 31455240, 2019). "BDNF is a neurotrophin that plays an important role in plasticity of the central nervous system and is also involved in the pathogenesis of neurological diseases." (PMID 31798417, 2019). "Future work will investigate the significance of the PPARγ-BDNF signaling on ameliorating behavior and synaptic plasticity in neurological diseases by inhibiting the BDNF receptor (TrkB)." (PMID 31614739, 2019). "BDNF level in the brain is often decreased in many neurological disorders including Huntington disease, wherein overexpression of BDNF in mice models leads to an improvement of cognitive function." (PMID 30871545, 2019). "When used to treat nervous system diseases, acupuncture enhances cell proliferation and neuroblast differentiation by increasing the levels of brain-derived neurotrophic factor (BDNF) and phosphorylated cyclic AMP response element-binding (CREB) protein." (PMID 31379957, 2019). "Accumulating evidence suggests that a decrease in brain-derived neurotrophic factor (BDNF) level induces a variety of psychiatric and neurological disorders." (PMID 29540150, 2018). "The most probable mode of action of energy restriction on neurological disorders is via BDNF signalling." (PMID 29465826, 2018). "Our and other studies suggest that patients with BDNF deficit are prone to neurological disorders and that clinical symptoms are significantly improved after amelioration of BDNF loss." (PMID 30115946, 2018). "Experimental or observational studies of people with neurological disorders who undertook an exercise intervention with BDNF as an outcome measure." (PMID 29057125, 2017). "Brain-derived neurotrophic factor (BDNF) exerts substantial protective effects for neurological disorders." (PMID 28243312, 2017). "There are growing numbers of studies aiming to elucidate the impact of aerobic exercise on BDNF levels in people affected by neurological disorders." (PMID 29057125, 2017).